PRRT1 (proline rich transmembrane protein 1)
Description:
Required to maintain a pool of extrasynaptic AMPA-regulated glutamate receptors (AMPAR) which is necessary for synapse development and function. Regulates basal AMPAR function and synaptic transmission during development but is dispensable at mature hippocampal synapses. Plays a role in regulating basal phosphorylation levels of glutamate receptor GRIA1 and promotes GRIA1 and GRIA2 cell surface expression.
Synonyms: DSPD1; SynDIG4; C6orf31; NG5; IFITMD7
Tractability: Antibody: UniProt places it where antibodies can reach, with medium confidence; UniProt predicts a signal peptide or a membrane-spanning region; its Gene Ontology location is reachable by antibodies, with medium confidence. PROTAC: its protein half-life has been measured.
Gene: Protein-coding gene on chromosome 6 (32,148,323 to 32,153,083, reverse strand). Ensembl gene ENSG00000204314.
Subcellular location: Cell membrane; Synapse
Gene Ontology:
Molecular function: signaling receptor regulator activity
Biological process: long-term synaptic depression; protein localization to cell surface; protein phosphorylation; regulation of AMPA receptor activity; synapse organization
Cellular component: glutamatergic synapse; plasma membrane; postsynaptic membrane; synapse; membrane; postsynaptic density membrane; synaptic vesicle membrane
Genetic constraint (gnomAD): Loss-of-function variants: 8 observed, 17.26 expected, observed/expected ratio (o/e) 0.46, 90% interval 0.27 to 0.84. The upper end of that interval is the gene's LOEUF score, 0.84, which puts it in group 3 of 6, group 1 being the genes least tolerant of losing a copy. Missense variants: 315 observed, 338.25 expected, observed/expected ratio (o/e) 0.93, 90% interval 0.85 to 1.02. Synonymous variants: 176 observed, 167.35 expected, observed/expected ratio (o/e) 1.05, 90% interval 0.93 to 1.19.
Homologues: Orthologues: chimpanzee PRRT1 (100% identical), macaque PRRT1 (98% identical), mouse Prrt1 (97% identical), dog PRRT1 (96% identical), pig PRRT1 (96% identical), rat Prrt1 (63% identical). Paralogues in human: PRRT1B (21% identical), PRRT2 (18% identical), TRARG1 (10% identical), TMEM233 (7% identical).
Diseases named in the same sentence as PRRT1 in open-access papers:
PRRT1 is named in the same sentence as 18 diseases in open-access papers, as found by Europe PMC text mining. Sharing a sentence is not in itself a finding about the gene and the disease. The quoted sentences say what the papers report.
Alzheimer disease (2 papers, 2021 to 2025). A progressive, neurodegenerative disease characterized by loss of function and death of nerve cells in several areas of the brain leading to loss of cognitive function such as memory and language. "Perhaps, boosting the activity of SynDIG4/PRRT1 might increase the reserve pool of extrasynaptic AMPARs to promote cognitive function in disorders associated with memory loss, such as Alzheimer’s disease." (PMID 33964729, 2021).
asthma (2 papers, 2024 to 2025). "For instance, cg17272563 (PRRT1) not only showed a significant association with asthma but also satisfied reverse MR analysis, highlighting its role in the causal pathway of asthma development." (PMID 39640897, 2024). "Reverse MR analysis also revealed a robust reverse causal relationship between cg17272563 (PRRT1) and asthma." (PMID 39640897, 2024). "Our study contributes a novel epigenetic perspective, proposing that PRRT1 may elevate the asthma risk through DNA methylation modifications." (PMID 39640897, 2024). "This suggests that changes at this methylation site may influence asthma risk, and conversely, asthma may affect the methylation status of cg17272563 (PRRT1)." (PMID 39640897, 2024). "Some overlap was detected with DMRs associated with maternal pregnancy asthma status (in gene PPT2; PRRT1) and maternal ever asthma (HOXA genes)." (PMID 40349045, 2025). "Consequently, it is essential to further explore the mechanisms of interaction between PRRT1 and asthma." (PMID 39640897, 2024).
allergic disease (1 paper, 2024). An immune response that occurs following re-exposure to an innocuous antigen, and that requires the presence of existing antibodies against that antigen. "A total of 55 CpG sites were found to significantly impact the risk of 5 site-specific allergic diseases, with 4 CpG sites exhibiting cross-allergic effects: cg17272563 (PRRT1), cg03689048 (BAT3), cg20069688 (STK19), and cg20513976 (LIME1)." (PMID 39640897, 2024). "Reverse MR analysis further revealed bidirectional causal relationships between allergic diseases and DNA methylation at CpG sites cg03689048(BAT3), cg17272563 (PRRT1), and cg20069688 (STK19)." (PMID 39640897, 2024). "The role of PRRT1 in allergic diseases may be attributed to the involvement of AMPAR in neuro-immune interactions, where the nervous and immune systems closely influence each other through signaling, especially during inflammatory responses." (PMID 39640897, 2024).
cognitive decline (1 paper, 2021). "Furthermore, DMRs annotated to MORN4, AIRE, LY6G5C, and PRRT1 were identified for both rates of cognitive decline as measured by the slopes of mPACCdigit/mPACCtrailsB and CDR-SB." (PMID 34654479, 2021).
lung carcinoma (1 paper, 2024). "A large-scale genome-wide interaction study also validated the association of PRRT1-related SNPs with the risk of lung cancer." (PMID 39640897, 2024).
memory loss (1 paper, 2021). "In particular, the SynDIG4/PRRT1 AMPAR auxiliary factor might reflect a potential target for interventions involved in memory impairments." (PMID 33964729, 2021).
nodular sclerosis (1 paper, 2013). "SNP rs9296009 in PRRT1 (proline-rich transmembrane protein 1) was associated with IGP23 (p = 3.79×10−08) while variants in PRRT1 previously showed associations with nodular sclerosis and Hodgkin lymphoma." (PMID 23382691, 2013).
neurodevelopmental disorder (1 paper, 2021). A behavioral and cognitive disorder with onset during the developmental period that involves impaired or aberrant development of intellectual, motor, or social functions. "Little is known about the function of PRRT1 although aberrant methylation of this gene has been related to neurodevelopmental disorders and to hepatic tumorigenesis." (PMID 33541404, 2021).
PRRT1 also shares sentences with these, for which no sentence is quoted: breast carcinoma (2 papers); cancer (2); tumor (2); autism (1); benign tumors (1); Cognitive impairment (1); colon cancer (1); neuroblastoma (1); tetanus (1); Wilms tumor (1).